TIGIT (T cell immunoreceptor with Ig and ITIM domains)
Diseases named in the same sentence as TIGIT in open-access papers (continued):
Sharing a sentence is not in itself a finding about the gene and the disease.
hematological malignancies (23 papers, 2020 to 2025). "High TIGIT expression, a marker of exhausted NK and T cells, is associated with disease progression and immune evasion in various hematologic malignancies." (PMID 41357215, 2025). "Collectively, these studies provide compelling support for the continued advancement of immunotherapies targeting the TIGIT axis in hematologic malignancies." (PMID 41357215, 2025). "Due to its role in immune evasion, TIGIT has emerged as a promising therapeutic target in hematologic malignancies." (PMID 40723175, 2025). "TIGIT, an emerging IC molecule, is gaining attention in hematological malignancies and is seen as a potential therapeutic target." (PMID 39391310, 2024). "In this section, we primarily consolidate the findings from preclinical studies that assess the potential of anti-TIGIT therapy in treating both solid and hematological malignancies." (PMID 38229100, 2024). "The expression of TIGIT is also typically upregulated and indicates poor clinical outcomes in several hematologic malignancies." (PMID 37291608, 2023). "In conclusion, these studies support the co-inhibition of TIGIT and PD-1/PD-L1 in treating hematological malignancies." (PMID 37291608, 2023). "In this review, we focus on the immunomodulatory role and mechanism of TIGIT, discuss its potential as an immune target in hematological malignancies." (PMID 36605439, 2022). "In summary, these researches supported the progress of immunotherapy targeting the TIGIT axis in hematological malignancies." (PMID 36605439, 2022). "Up-regulation of TIGIT has been reported in various hematological malignancies, which predicts poor outcomes." (PMID 36605439, 2022). "Ultimately, antibodies against TIM-3, LAG-3, and TIGIT are all under investigation for the treatment of various solid and hematologic malignancies." (PMID 33804869, 2021). "In summary, the BM-infiltrating γδ T cells co-expressed PD-1, TIM-3, and CD39 with TIGIT in both hematological malignancies." (PMID 34820398, 2021). "In hematologic malignancies, TIGIT has emerged as a key immune checkpoint." (PMID 40723175, 2025). "Similarly, strategies targeting TIGIT in combination with PD-L1 inhibitors have demonstrated promising potential in both solid tumors and hematologic malignancies." (PMID 40356928, 2025). "LAG-3, TIM-3, and TIGIT blockade have shown promising activity in many hematologic malignancies." (PMID 37920162, 2023). "In this review, we focus on the role of TIGIT in hematological malignancies and discuss therapeutic strategies targeting TIGIT, which may provide a promising immunotherapy target for hematological malignancies." (PMID 36605439, 2022). "Ongoing clinical trials targeting TIGIT in hematological malignancies." (PMID 36605439, 2022). "Simultaneously, the parallel development of therapeutic antibodies targeting inhibitory molecules associated with immune exhaustion (such as PD-1, but also TIGIT, and LAG-3) has led to a revolution in oncology with dramatic benefits in a growing list of solid and hematologic malignancies." (PMID 32117816, 2020). "Although crucial inhibitory mechanisms remain unknown, growing evidence suggests that TIGIT is a key T cell immune checkpoint in hematological malignancies." (PMID 32787882, 2020). "Although evaluated only in solid tumors, this evidence indicates that TIGIT could represent a potentially promising target also for the treatment of hematological malignancies." (PMID 32610578, 2020). "Since CD155 is expressed in a broad range of malignancies including blood cancers, therapeutic blockade of TIGIT might have broad implications for immunotherapy against hematological malignancies." (PMID 32787882, 2020). "Therefore, targeting TIGIT may be an effective approach for ICB therapy in hematologic malignancies." (PMID 41357215, 2025).
hematological malignancies (continued). "Bone marrow resident NK cells exhibit a unique immunosuppressive phenotype with higher surface CXCR6 and express higher levels of TIGIT than circulating NK cells at steady state, suggesting anti-TIGIT approaches may be particularly important for treatment of hematologic malignancies." (PMID 37654497, 2023). "Thus TIGIT appears to be an important mechanism of immune evasion for hematologic malignancies, but further understanding of its significance and whether it is an effective target for therapy remains unknown." (PMID 37920162, 2023). "Even though therapeutic strategy targeting TIGIT has provided evidence of encouraging efficacy in hematological malignancies, the immune-related adverse events (irAEs) mediated by over-activated T cells may result in multiple organ dysfunction and poor prognosis." (PMID 36605439, 2022). "Therefore, targeting TIGIT may be an effective approach for ICB therapy in hematological malignancies." (PMID 36605439, 2022). "Beyond the traditional checkpoint molecules, several other receptors are under investigation as therapeutic targets in hematologic malignancies—including TIM-3, LAG-3, and TIGIT." (PMID 33804869, 2021). "Despite the considerable efficacy of blocking TIGIT in preclinical research and clinical trials for hematological malignancies, the distribution characteristics of TIGIT in γδ T cells from AML have not been comprehensively investigated." (PMID 38711501, 2024). "Additionally, antibodies targeting other checkpoint molecules, including TIM3, TIGIT, and LAG-3, have been developed and are currently undergoing early clinical trials in patients with hematological malignancies." (PMID 39766080, 2024). "Furthermore, the downregulation of TIGIT can potentially restore T-cell function and improve IFN-γ production in hematological malignancies." (PMID 38711501, 2024). "Expression analyses of corresponding immune effector cells derived from the BM revealed an increased expression of TIGIT, PD-1, TIM-3, and CD39 on γδ TCR cells in comparison to CD4+ cells, which was similar to that on CD8+ effector cells in both hematologic malignancies." (PMID 34820398, 2021). "TIGIT, PD-1, TIM-3, and CD39 were more frequently expressed by γδ T cells in comparison to the corresponding CD4+ T cell population, with expression levels that were similar to that on CD8+ effector cells in both hematologic malignancies." (PMID 34820398, 2021). "TIM-3, TIGIT, and CTLA-4 upregulation in CD8+ T cells with exhaustion features has been reported in chronic lymphocytic leukemia (CLL), AML, and post-allogenic HSCT B-ALL relapse, and targeting these exhaustion markers improved the outcome of hematological malignancies." (PMID 36901957, 2023). "However, the mechanism and function of TIGIT in hematological malignancies have not been comprehensively studied." (PMID 36605439, 2022).
immune dysfunction (8 papers, 2015 to 2025). "TIGIT expression by CD8+ T and NK cells and PD-1 by NKT cells suggest a spectrum of immune dysfunction, encompassing both hyperactivation and features of exhaustion." (PMID 39764446, 2024). "Additionally, these patients showed upregulation of immune exhaustion markers such as LAG3, PDCD1, TIGIT, CTL4, and C-ECM, TITR signatures, indicating a state of immune dysfunction." (PMID 38951896, 2024).
digestive system tumors (3 papers, 2022 to 2025). "This study summarized the mechanism of CD155/TIGIT in regulating immune cells and its role in the occurrence and development of digestive system tumors, aiming to provide a new perspective for immunotherapy of digestive cancers." (PMID 35433470, 2022). "This review summarizes the biological function and mechanism of TIGIT/CD155 in immune cells and the latest research progress in digestive system tumors." (PMID 35433470, 2022).
hematological cancers (3 papers, 2021 to 2025). "TIGIT stands out as a highly expressed marker on exhausted NK and T cells, and its high expression was involved in disease progression and the immune escape in various hematological tumors, indicating the promising value of TIGIT blockade treatment." (PMID 38229100, 2024). "These suggest that the role of TIGIT may vary between solid tumors and hematological cancers." (PMID 38229100, 2024).
infectious disease (3 papers, 2018 to 2025). A disorder directly resulting from the presence and activity of a microbial, viral, or parasitic agent in humans. "Recently, a function of TIGIT was identified in the prevention of pathological tissue damage in an infectious disease setting." (PMID 34043881, 2021).
kidney (3 papers, 2018 to 2023). "After i.v. administration of donor-derived Mregs, increased TIGIT+ Treg frequencies are observed in the peripheral blood of prospective kidney transplant recipients." (PMID 30030423, 2018). "Preoperative administration of donor-derived Mregs to living-donor kidney transplant recipients results in an acute increase in circulating TIGIT+ Tregs." (PMID 30030423, 2018).
adenocarcinoma (2 papers, 2023 to 2025). A common cancer characterized by the presence of malignant glandular cells. "TIM-3, TIGIT, and LAG-3 show differential expression in squamous-cell and adenocarcinoma, varying by age and gender." (PMID 40647508, 2025). "Therefore, we investigated the potential of the immune checkpoint molecules TIM-3, TIGIT, and LAG-3 in squamous-cell carcinoma (SCC) and adenocarcinoma (ADENO) of the urinary bladder." (PMID 40647508, 2025).
cardiovascular diseases (2 papers, 2020 to 2024). "This exploration is particularly focused on conditions characterized by elevated TIGIT expression, especially in cardiovascular diseases." (PMID 38375475, 2024). "Expression of TIGIT and PD1 by CD4 T cells have been associated with immune activation and increased risk of cardiovascular diseases in HIV infected patients as measured by 2-year change in coronary artery calcium." (PMID 32714317, 2020). "The heightened expression of TIGIT ligands raises the question of whether it signifies a potential risk of cardiotoxic irAEs or suggests a protective function of TIGIT against cardiovascular diseases." (PMID 38375475, 2024). "However, the mechanism in which TIGIT can contributes to cardiovascular disease is largely unknown." (PMID 32714317, 2020).
hematological neoplasms (1 paper, 2024). "TIGIT can be targeted by selective compounds such as the anti-TIGIT humanized mAb vibostolimab, resulting in effective antitumor responses against both solid tumors and hematological neoplasms." (PMID 38791909, 2024).
inflammation (1 paper, 2024). Aberrant reaction of the microcirculation characterized by movement of fluid and leukocytes from the blood into extravascular tissues. "In IBD patients with active intestinal inflammation, the activation of CD25+CD45A+ Treg cells by circulating CD38+effector T cells increased, and the frequency of TIGIT+ cells decreased." (PMID 38202824, 2024).
TIGIT also shares sentences with these, for which no sentence is quoted: multiple myeloma (22 papers); cholangiocarcinoma (4); Merkel cell carcinoma (4); atopic dermatitis (3); Granuloma (3); small cell lung carcinoma (3); Adrenocortical carcinoma (2); Allergy (2); anaplastic thyroid cancers (2); Arthritis (2); chromophobic renal cell cancer (2); Chronic Myeloid Leukemia (2); dermatomyositis (2); gastric adenocarcinoma (2); Hepatitis B- (2); Lewis lung carcinoma (2); Oral Cancer (2); psoriatic arthritis (2); rectal adenocarcinoma (2); undifferentiated pleomorphic sarcoma (2); abortion (1); acral melanomas (1); acute kidney injury (1); acute leukemia (1); acute viral hepatitis (1); aneurysm (1); autoimmune encephalitis (1); autoimmune glomerulonephritis (1); bacterial infection (1); brain cancer (1).
A further 48 diseases each share a sentence with TIGIT in 1 paper.